ENSG00000295599 (novel transcript)
Gene: Long non-coding RNA gene on chromosome 1 (240,481,253 to 240,486,728, forward strand). Ensembl gene ENSG00000295599.
Gene Ontology:
Biological process: SRP-dependent cotranslational protein targeting to membrane, signal sequence recognition
Cellular component: signal recognition particle, endoplasmic reticulum targeting